CDK4 (cyclin dependent kinase 4)
Diseases named in the same sentence as CDK4 in open-access papers (continued):
Sharing a sentence is not in itself a finding about the gene and the disease.
tumor (continued). "Immunohistochemically, the tumor cells were positive for CD-34 and negative for CDK4, MDM2, and P16." (PMID 40777097, 2024). "This may be possibly due to decreased expression of cyclin D1, cyclin-dependent kinase 4 (CDK4) and CDK6 and increased expression of p27, indicating that CMTM7 acts as a tumor suppressor by inhibiting cell cycle progression in HCC." (PMID 38223763, 2024). "In some cells and tumours, insensitivity is predicted by the absence of active T172‐phosphorylated CDK4, mostly due to elevated p16/CDKN2A levels consequent to defects or cyclin E‐dependent inactivation of pRb." (PMID 36453028, 2024). "Our findings may now provide a mechanistic framework on the interplay between CDK4/CDK6 blockade and mTORi resulting in increased tumor control and prevent the acquisition of palbociclib resistance." (PMID 38954773, 2024). "Therefore, CDK4/6 inhibitors can enhance the ubiquitination function of SPOP, promoting anti-tumor immune responses." (PMID 39315102, 2024). "Dalpiciclib and palbociclib all displayed a concentration-dependent inhibition of tumor growth in HNMM-PDC harboring CDK4 amplification, but there was no inhibitory effect on HNMM-PDC with CDK4 wild type cells." (PMID 38807144, 2024). "Agaimy and his colleagues found that both MDM2 immunohistochemistry and FISH provided a positive result in FDCS, but the CDK4 was negative in the tumor cells." (PMID 38297323, 2024). "Furthermore, the anti-tumor activity of elacestrant translates into various PDX models representing intrinsic and acquired CDK4/6 inhibitor resistance." (PMID 39767607, 2024). "Conversely, several of the SCLC-Y lines that we now identify to be SMARCA4-UT have previously been shown to be sensitive to CDK4/6 inhibitors, and consistent with this SMARCA4-deficiency, has been shown to be a strong predictor of sensitivity to CDK4/6 inhibitors in NSCLC and SCCOHT tumor models." (PMID 38180245, 2024). "Moreover, the combination of CDK4/6i and MYC-degrading molecule A80.2HCl shows an additive effect on killing tumor cells both in vitro and in vivo." (PMID 38424044, 2024). "Tumours were classified as done previously in three groups based on their CDK4 phosphorylation status: A (absence of phosphorylation), L (low phosphorylation) and H (high phosphorylation)." (PMID 36453028, 2024). "Immunohistologically, the nuclei of tumor cells were positive for MDM2 and CDK4." (PMID 39297994, 2024). "Amplification of MDM2 and CDK4 genes can be detected in various mesenchymal and nonmesenchymal neoplasms." (PMID 38275873, 2024). "Rhopaladin B exhibited inhibitory activity against CDK4 (cyclin-dependent kinase 4) and c-erbB-2 kinase, with IC50 values of 12.5 and 7.4 μg/mL, respectively, indicating potential significant cytotoxicity to human tumor cells." (PMID 38474445, 2024). "As part of the secondary objective of the clinical trial to investigate biomarkers of resistance to CDK4/6i through a correlative multi-omics analysis, we generated WES and RNA-seq data from tumor biopsies and ctDNA samples from patients who participated in the phase II portion." (PMID 38503755, 2024). "At the same time, the 1st released core was internalized by tumor cells and degraded by intracellular GSH, to realize a 2nd release of CDK4/6i in tumor cells, which induced an up‐regulated expression of CXCL10 and CCL5, and thus a significantly increased tumor infiltration of T cells." (PMID 38634209, 2024). "Although several preclinical studies have implied the potential applicability of CDK4/6 inhibitor for this rare tumor, no clinical evidence has been documented so far." (PMID 38369555, 2024).
tumor (continued). "Surprisingly, treatment with an anti-CCL2 antibody of KPC tumors treated with MEK and CDK4/6 inhibitors, along with an EZH2 blockade, led to a significant reduction in anti-tumor effects, highlighting that NK cell accumulation was critical for tumor regression." (PMID 38339310, 2024). "Another rationale for abemaciclib in prophylactic and therapeutic settings is the fact that aberrant CDK4/6 function triggers tumor immune evasion and orchestrates an immunologically cold TME – regardless of tumor mutational burden." (PMID 38986222, 2024). "CDK4/6 inhibitors, approved by the FDA in 2015 for the first-line treatment of HR(+)/HER2 (–) advanced breast cancer, primarily inhibit the phosphorylation of the retinoblastoma gene (Rb), blocking the G1 phase of the cell cycle in tumor cells." (PMID 38352877, 2024). "Additionally, the administration of CDK4/6 inhibitor Palbociclib has been shown to promote CD8+ T cell differentiation into memory-like phenotypes, thereby bolstering the anti-tumor effects of adoptive T cell therapy." (PMID 38750022, 2024). "Dysregulation of the Cyclin D-CDK4/6-INK4-Rb pathway and subsequent unchecked cell proliferation, is a common feature of human cancers; CDK4/6 activity is therefore a key target to attenuate tumour growth." (PMID 41146951, 2024). "This indicates that the capacity of CDK4/6i‐induced senescence to activate anti‐tumor immunity is probably similar to that of DNA‐damaging agent‐induced senescence, despite the reduced secretion of pro‐inflammatory and pro‐angiogenic SASP in the CDK4/6i‐group." (PMID 37854019, 2024). "Therefore, inhibition of CDK4/6 kinases leads to an increase in PD-L1 protein levels by hindering cyclin D-CDK4-mediated SPOP, resulting in a decrease in the number of tumor-infiltrating lymphocytes (TILs) in tumors." (PMID 39593745, 2024). "The efficacy results were positive for several cohorts, including olaparib in various tumor types with BRCA1/2-inactivating mutations and palbociclib in CDK4-amplified STS, and they were negative for seven cohorts." (PMID 37998367, 2023). "Cell line and original tumor share the majority of CNV alterations, including losses in Chr 9/10 that included PTEN and MGMT and gains in Chr 20, which included amplification of PDGFRA, CDK4, and MDM2." (PMID 37958846, 2023). "By targeting key components of the CDK4 pathway, it may be possible to halt the cell cycle progression of GBM cells and suppress tumor growth." (PMID 37593751, 2023). "Interestingly, the tumor cells in two TNBC groups displayed different expression patterns of the critical immunotherapeutic targets, such as PD-1/L1, CTLA4, CD47, CDK4/6, PARP1/2 and DDR1/2." (PMID 36998014, 2023). "Third, FOXM1 mediates tumor cell resistance to irradiation, chemotherapies, and targeted therapeutics, including PI3K inhibitors, EGFR inhibitors, and CDK4/6 inhibitors, among others." (PMID 37686402, 2023). "In the present case, co-copy number amplification of CDK4 and MDM2 may have cooperatively upregulated cell cycle and promoted tumor progression." (PMID 38012788, 2023). "Moreover, Western blot analysis showed that the CDK4 and CDK6 expressions were downregulated, whereas p21 expression was upregulated in tumor tissues from mice bearing QKI‐5 overexpressing cells compared with mice bearing control cells." (PMID 36172919, 2023).
tumor (continued). "Moreover, considering tumor heterogeneity and the small size of our population, looking for ESR1 mutations may not be sufficient, since other mutations, such as in the MAPK, PI3K/AKT/mTOR, and CDK4/6 pathways, have been demonstrated to be involved in the mechanisms of resistance." (PMID 36831647, 2023). "CDK4/6 inhibition was shown to downregulate homologous recombination, sensitising breast and ovarian cancer cell lines to PARP inhibition to inhibit cell growth, particularly in tumours with high levels of MYC expression." (PMID 37430137, 2023). "Moreover, inactivation of STING in Cdk4−/− and Cdk6−/− cancer cells reversed the hyper-activation of type I IFN response and the anti-tumor effect of Cdk4/6 knockout." (PMID 37833461, 2023). "Immunohistochemically, the tumor tested positivity for MDM2, CDK4, and p16." (PMID 37881487, 2023). "Based on our understanding of the diverse mechanisms of resistance post tumor progression on ET and CDK4/6i, a personalized rather than one-size-fits-all approach will be the optimal strategy." (PMID 37684290, 2023). "The study offered RNA analysis for CDK4 and CDKN2A in the archival tumor material with the assumption that if a biomarker expression fitting with the inclusion criteria was found, then the screening at baseline would render a highly probable similar RNA expression." (PMID 37875500, 2023). "The HPV-positive-related subtype also exhibited higher expression in tumor growth, and some studies have indicated that HPV virus may dysregulate the cell cycle to promote cancer cell growth (e.g., CDK4 and MCM2, both members of HNSC88)." (PMID 37685875, 2023). "Additionally, the KEGG pathway analysis highlighted the involvement of CDK4 in the MAPK signaling pathway, further emphasizing its relevance in tumor growth." (PMID 37593751, 2023). "The tumor specimen was sent for further analysis for next-generation sequencing (NGS; ACTOnco+, ACT Genomics), which mainly disclosed TPM3::NTRK fusion (Appendix Fig A1), and MDM2/CDK4 gene amplification." (PMID 36652666, 2023). "For monotherapy of CDK4/6i, the PDX model showed good sensitivity in the first week of administration but subsequently displayed a rapid tumor volume increase, suggesting that the tumor had acquired drug resistance." (PMID 37452037, 2023). "Although we have not studied the role of type III IFN in Cdk4−/− and Cdk6−/− tumor growth, we have transplanted Cdk4−/− and Cdk6−/− cancer cells into Ifnar1−/− mice." (PMID 37833461, 2023). "Furthermore, CDK4/6 inhibitors were also reported to promote the formation of stem or memory-like cytotoxic CD8+ T cells, thus leading to a sustained anti-tumor response to ICIs." (PMID 37631380, 2023). "Therefore, effective inhibition of CDK4/CDK6 expression can lead to cell cycle arrest, resulting in tumor growth suppression." (PMID 38049779, 2023). "Considering that extensive anti-tumor effects of CDK4/6i, especially the mechanism of action, cell cycle alternation in HER2+ BC, and the cyclinD/CDK 4/6 compound are directly downstream of the HER2 pathway, it is reasonable to apply CDK4/6i to HER2+ BC." (PMID 38293701, 2023). "The amplification of AURKA was found in tumor biopsies from patients resistant to CDK4/6i treatment, while no alterations were detected in samples from CDK4/6i-sensitive patients." (PMID 37835528, 2023). "In our drug assays, however, the response to CDK4/6 inhibitors and Everolimus did not correlate with the receptor status of the tumor organoids." (PMID 37509265, 2023). "Finally in patient 3, amplifications of the CDK4 (13.6 copies) and KRAS (3.9 copies) genes were detected in the primary tumor." (PMID 37108696, 2023). "Our results showed that the knockdown of CCND1b downregulated the ratio of CCND1b/a, inhibited the CDK4/CyclinD1‐pRB‐E2F1 signalling pathway and prevented tumour cells from passing through the G1‐S transition resulted in cycle arrest, thereby decreasing the chemoresistance." (PMID 36915230, 2023).
tumor (continued). "Besides, we found CDK4 and MDM2 amplifications with upregulated phospho-Rb in the recurrent tumor and its xenografts, suggesting the multiple deregulated cell cycle mechanisms to support tumor progression and facilitate xenograft formation in the present case." (PMID 38012788, 2023). "In other words, analogous to CDKN2A/B HD, CDK4 and MDM2 co-amplification might accelerate tumor progression and may induce a malignant phenotype." (PMID 38012788, 2023). "The colony-forming assays showed this combination harbored significantly better anti-tumor activity than the single drug, indicating the LRPPRC-mediated OXPHOS could also promote CDK4/6i resistance in LUAD." (PMID 37452037, 2023). "Higher activation of CDKs, including CDK1 and CDK4, was observed in EPCAM− tumour cells compared with in EPCAM+ and Rhoj-KO EPCAM− cells after chemotherapy suggesting that RHOJ enables EMT tumour cells to progress in the cell cycle and continue DNA synthesis after chemotherapy." (PMID 36949199, 2023). "We did not detect NTRK fusion or MDM2/CDK4 amplification in the residual tumor tissue, which was in line with the results of cfDNA-based assay at day 14 after resection." (PMID 36652666, 2023). "Signaling pathway resistance may stem from disrupted IFN-γ signaling in tumor cells, or the dysregulation of oncogenic signaling pathways (WNT–β-catenin, CDK4/6, MAPK cascades)." (PMID 37345111, 2023). "In our study, CDK4 amplification was more common in periventricular lesions (group II), which may reflect the characteristics of NPC-like GBM and tumor localization." (PMID 37744696, 2023). "Additionally, the combination of CDK4/6i and anti-HER2 targeting has been found to overcome anti-HER2 resistance, synergistically inhibiting cell proliferation, controlling tumor growth in vivo, and delaying tumor recurrence." (PMID 38293701, 2023). "Notably, amplifications of CDK4 and MDM2 and gain of PDGFRA, together with chromosome 4p gain were identified as newly acquired CNAs in YMG25R, as compared to the initial tumor YMG25P." (PMID 38012788, 2023). "Overexpression of cyclin E was previously reported as a mechanism to evade CDK4/6 inhibition because it can activate CDK2 and Rb phosphorylation to re-enter the cell cycle, as observed in preclinical studies and retrospective analyses of tumor tissues." (PMID 36792625, 2023). "To test the potential for simultaneous inhibition of CDK4/6 and OLIG2 to produce a greater anti-tumor effect compared to either intervention alone, we treated replicate G-Smo mice with POx-Palbo plus CT-179 and then compared PK effects and efficacy versus CT-179 alone or POx-Palbo alone." (PMID 37333134, 2023). "Similarly, tumor cells can also acquire immune tolerance through MAPK, WNT, CDK4/6, and PTEN signaling pathways." (PMID 36982415, 2023). "As palbociclib inhibits both CDK4 and CDK6, we further addressed the effects of CDK6 on tumor growth and immunogenicity by analyzing online databases to determine whether CDK6 expression is related to the prognosis of patients." (PMID 37833461, 2023). "PEG10-positive group showed a trend toward shorter CDK4/6 inhibitor PFS than PEG10-negative group (p = 0.144), indicating that PEG10 protein level in the tumor sample may serve as a novel biomarker to predict palbociclib efficacy." (PMID 38017459, 2023). "Thus, the exclusion ZWINT intron in the tumour samples is predicted to lead to higher levels of total ZWINT expression, consequent elevation of cyclin D1 and E1 and cyclin dependent kinase 4 expression and promotion of cell proliferation." (PMID 37924098, 2023). "We observed that both RBsig and CCNE1 predicted low sensitivity to CDK4/6i in MKShi/ERSlo tumours, whereas the IRPS did not provide informative results." (PMID 37935787, 2023). "In addition, similar to YMG25R parent tumor, YMG25R xenograft cells highly expressed phospho-PDGFRA, -AKT, and -ERK as well as CDK4 and MDM2, and phospho-Rb, as compared to sham control." (PMID 38012788, 2023).
tumor (continued). "In our study, all 18 tested WDLs were 12q13-15 amplified, including 17 MDM2-amplified cases and 1 FRS2-amplified/MDM2-nonamplified/CDK4-nonamplified tumor (case 4)." (PMID 36059611, 2022). "Acquired resistance is the main reason for the therapeutic failure of CDK4/6 inhibitors in RB-proficient tumors, where tumor cells can acquire the ability to survive in the absence of CDK4/6 function." (PMID 35892870, 2022). "In fact, in vitro studies have demonstrated the anti-tumour effect of 800 μM melatonin for 72 h, as it is able to inhibit tumour growth through the downregulation of cyclin-dependent kinases 2 and 4 (CDK2 and CDK4) in ovarian cancer cell lines PA-1 and OVCAR-429." (PMID 36670948, 2022). "There is also emerging evidence that CDK4/6 inhibition can block metabolic pathways, potentially leading to the control of tumor progression that is independent of RB status." (PMID 35892870, 2022). "CDK4/6 act to control cell cycle progression through the early G1 phase and are positively regulated by the interaction with cyclins (e.g., D1/D2/D3) and negatively regulated by tumour suppressors (e.g., p16 INK4 A) that stop CDK4/6 interaction with D-type cyclins." (PMID 36135204, 2022). "Currently, there are no clinically available biomarkers for prescribing CDK4/6 inhibitors except for ER expression mainly from primary tumour tissues." (PMID 36028895, 2022). "Although the KRAS-G12V transgene is expressed in multiple tissues, tumor induction and subsequent senescence due to an absence of CDK4 expression were only detected in the lung." (PMID 36051751, 2022). "In addition, in a B16F10 flank tumor model, pharmacological FAK inhibition reduced tumor size, increased FAK nuclear localization, and reduced CDK4/6 protein expression." (PMID 35525274, 2022). "The tumor suppressor effect of miR-124 was also observed through the inhibition of cell cycle-related cyclin D1, cyclin-dependent kinase 2 (CDK2), cyclin-dependent kinase 4 (CDK4), and cyclin-dependent kinase 6 (CDK6)." (PMID 35326471, 2022). "Disruption of ccnd loci and that of cdk4 (but not cdk6) in MEFs, as well as treatment of tumor cell lines with CDK4 inhibitors, also stabilize PD-L1 at the protein level." (PMID 36051751, 2022). "Cyclin-dependent kinase CDK4 and CDK6 are hyperactivated in various tumor." (PMID 36376832, 2022). "During the treatment suspension phase, tumor progressed rapidly upon the removal of palbociclib (days 15-31, treatment off), reflecting the cytostatic rather than cytotoxic effect of CDK4/6 inhibition." (PMID 35546399, 2022). "Furthermore, researchers found that pharmacological inhibitors of cyclin-dependent kinase 4 (CDK4) and CDK6 boost tumor immunogenicity." (PMID 36304306, 2022). "In the PDO model, both the size and number of tumor organoids were significantly decreased in the presence of Reb, but not in the presence of abemaciclib (Abe, CDK4/6 inhibitor, used as a control)." (PMID 35449080, 2022). "We then confirmed that abemaciclib (CDK4/6 selective inhibitor) could inhibit the proliferation of ascites cells, and the combination of abemaciclib and MS275 had synergistic anti-tumor effect." (PMID 35062876, 2022). "Despite significantly reduced proliferation, gene expression of key cell cycle regulators (p27, p21, CDK4, Cyclin D) within the LL/2 tumor cells were not significantly altered by metformin." (PMID 36672573, 2022). "Several studies have suggested that the CDK4/6 inhibitors bind to the ATP-binding pocket of CDK4 and CDK6 and block the cell proliferation in a wide range of tumors and reduce tumor growth in cancer xenograft models." (PMID 35938171, 2022). "For example, CDK4/6 inhibition restricts optimal T cells expansion, and when used in combination with BRAF/MEK-targeted therapies, depletes immune-potentiating myeloid subsets from the tumor microenvironment." (PMID 35444175, 2022).